RPE65 (retinoid isomerohydrolase RPE65)
Diseases named in the same sentence as RPE65 in open-access papers (continued):
Sharing a sentence is not in itself a finding about the gene and the disease.
Retinal dystrophy (continued). "Voretigene neparvovec is an approved retinal gene therapy for treatment of retinal dystrophies caused by bi-allelic mutations in RPE65." (PMID 33472769, 2022). "We report the case of a 40-year-old male with inherited retinal dystrophy, all features typical for the RPE65-associated RP, and marked macular atrophy." (PMID 36142423, 2022). "In 2018, voretigene neparvovec-rzyl (VN) was launched for gene therapy of RPE65-linked inherited retinal dystrophies (IRD) in the European Union." (PMID 36672611, 2022). "Simultaneously, natural history studies of disease progression in RPE65-associated retinal dystrophy demonstrated that these patients had slower anatomic progression with respect to photoreceptor cell loss than other forms of LCA." (PMID 34768969, 2021). "With few exceptions such as gene therapy for RPE65-associated retinal dystrophy, TES is currently the only evidence-based and clinically available method to slow down disease progression in RP." (PMID 33037922, 2021). "Since the recent approval of voretigene neparvovec-rzyl (Luxturna) for biallelic RPE65-associated retinal dystrophy, interest in gene therapy for monogenic inherited retinal dystrophies has grown." (PMID 33039401, 2021). "Biallelic causal variants in RPE65 can cause certain inherited retinal dystrophies (IRD), such as Leber’s congenital amaurosis (LCA) and early-onset severe retinal dystrophy (EOSRD)." (PMID 34830511, 2021). "Nine patients were identified with biallelic RPE65 mutations, corresponding to a prevalence rate of 9/187 = 5% among early onset retinal dystrophies." (PMID 31925606, 2020). "Recently, the U.S. FDA approved an AAV-RPE65 vector as a therapeutic reagent for LCA2 and other biallelic RPE65 mutation associated retinal dystrophies." (PMID 33107823, 2020). "RPE65-associated retinal dystrophy (RPE65-RD) is an early onset, progressive, severe retinal dystrophy." (PMID 32347917, 2020). "Nine of these patients had biallelic RPE65 mutations, arriving at an estimated prevalence rate of 9/187 = 5% among early onset retinal dystrophies." (PMID 31925606, 2020). "This has changed with the approval of a first gene therapy for a specific condition, RPE65-linked retinal dystrophy." (PMID 33374621, 2020). "It saw the first Food and Drug Administration (FDA) approval of gene therapies for certain forms of acute lymphoblastic leukemia, large B cell lymphoma, and biallelic RPE65-associated retinal dystrophy." (PMID 30805203, 2019). "LuxturnaTM, loaded with wildtype RPE65, will be given to patients with confirmed biallelic RPE65 mutation-associated retinal dystrophy to restore their vision within a few months." (PMID 31069169, 2019). "Luxturna is applied intraocularly and is an orphan drug designated for the cure of inherited retinal dystrophy caused by bi-allelic RPE65 mutations." (PMID 31608113, 2019). "This pharma company utilizes an AAV system to deliver RPE65 gene into the patients eye suffering from retinal dystrophy caused by RPE mutations." (PMID 31608113, 2019). "In December of 2017, Philadelphia-based Spark Therapeutics Inc. obtained the first FDA approval of LUXTURNATM for gene therapy to treat retinal dystrophy due to a mutation in the retinoid isomerohydrolase made from the RPE65 gene." (PMID 29997477, 2018). "This product, LUXTURNATM (voretigene neparvovec-rzyl; Spark Therapeutics, Inc., Philadelphia, PA), delivers a normal copy of the RPE65 gene to retinal cells for the treatment of biallelic RPE65 mutation–associated retinal dystrophy, a blinding disease." (PMID 30591984, 2018). "Mutations of the RPE65 gene in humans cause most frequently Leber congenital amaurosis, with a small percentage of severe early childhood onset retinal dystrophy." (PMID 28928775, 2017).
Retinal dystrophy (continued). "A growing number of genetic mutations have been identified over the past decades that can cause retinal dystrophy, among which mutations in the gene encoding the retinal pigment epithelial protein of 65 kDa (RPE65) are best characterized." (PMID 28280483, 2017). "For instance in the eye, where mutations in the RPE65 gene are the cause of inherited retinal dystrophy, gene therapy was used to introduce the RPE65 gene, leading to a reversal in blindness in patients." (PMID 28119578, 2016). "To date, a number of different RPE65 mutations have been reported in patients with retinal dystrophies classified as LCA, autosomal recessive EORD or arRP30,33,34." (PMID 27874104, 2016). "Intact RPE65 function is essential for vision, as mutations in the RPE65 gene cause several forms of inherited retinal dystrophies." (PMID 26694648, 2015). "Mutations in the RPE65 gene are associated with autosomal recessive early onset severe retinal dystrophy." (PMID 24466015, 2014). "Homozygous and compound heterozygous mutations in the RPE65 gene are associated with Leber’s congenital amaurosis (LCA) type 2 or with early onset severe retinal dystrophy (EOSRD), depending on the age of onset of severe visual impairment." (PMID 24466015, 2014). "Identification of these mutations reaffirms the diverse allelic heterogeneity of RPE65 in the pathogenesis of retinal dystrophies." (PMID 23878505, 2013). "By successfully replacing the defective RPE65 gene with a functional copy, Luxturna not only provided a groundbreaking treatment for patients with RPE65-associated retinal dystrophy but also initiated substantial investment and research into gene therapies for a broader spectrum of IRDs." (PMID 40869487, 2025). "Mutations in RPE65 cause a retinal dystrophy that is treatable with an approved gene therapy." (PMID 41051147, 2025). "Despite the lack of effective treatments for most retinal dystrophies, recent advances in gene therapy, particularly the approval of Luxturna for RPE65-associated retinal dystrophies, offer new hope for therapeutic intervention, with several ongoing clinical trials targeting other subtypes." (PMID 40002842, 2025). "The approval of voretigene neparvovec-rzyl (Luxturna®) for RPE65-associated retinal dystrophy marked a milestone in gene therapy, while ongoing clinical trials now explore gene editing (CRISPR), RNA-based correction strategies, optogenetics, and stem cell transplantation." (PMID 40731809, 2025). "Mutations in RPE65 cause a retinal dystrophy that is treatable with an FDA-approved gene therapy." (PMID 39975398, 2025). "Recent FDA endorsements of gene therapy for treating spinal muscular dystrophy (SMA) and RPE65 mutation-associated retinal dystrophy offer the promise that a multitude of rare neurological disorders may soon find therapeutic avenues through gene therapy." (PMID 38674235, 2024). "In a phase III randomized controlled trial (RCT) (NCT00999609), 31 participants (21 in the intervention group and 10 in the control group) with confirmed RPE65-associated retinal dystrophy received bilateral sequential subretinal injections of AAV2-hRPE65v2 (voretigene neparvovec, Luxturna)." (PMID 39598155, 2024). "There were two RPE65-associated retinal dystrophy trials for the approval of voretigene neparvovec-ryzl: the US and EU-based trial for original approval (NCT00999609), and a subsequent trial conducted in Japan with commercial approval granted in 2023 (NCT04516369)." (PMID 39336999, 2024). "However, RPE65-associated retinal dystrophies are reported to be relatively rare in Japan, with few documented cases detailing their clinical progression." (PMID 39359914, 2024). "Some hope may lie in AAV-gene therapy, which recently resulted in the approval of voretigene neparvovec (Luxturna®) for patients with biallelic RPE65 mutation-associated inherited retinal dystrophy." (PMID 38541080, 2024).
Retinal dystrophy (continued). "Voretigene Neparvovec (VN; brand name Luxturna®, Spark Therapeutics Inc., Philadelphia, PA, USA) is the first in vivo gene therapy for the eye approved for the treatment of retinal degeneration in patients affected by inherited retinal dystrophy caused by biallelic mutations in the RPE65 gene." (PMID 39062658, 2024). "Gene therapy in ophthalmology has garnered renewed interest in recent years since the 2017 FDA approval of voretigene neparvovec-rzyl (Luxturna), a subretinal gene therapy using the AAV2 virus vector to deliver human RPE65 cDNA in RPE65-associated retinal dystrophy." (PMID 37631054, 2023). "Notably, the term “gene therapy” encompasses much more than mere replacement therapy, the approach used for RPE65-associated retinal dystrophy." (PMID 38066762, 2023). "As such, RPE65-associated retinal dystrophy is an ideal target for gene therapy." (PMID 36324900, 2022). "Voretigene neparvovec-rzyl (Luxturna, Spark Therapeutics) already is available for the treatment of biallelic RPE65-associated retinal dystrophy, with further trials underway to treat CHM-, RS1-, RPGR-, MERTK-, ABCA4-, USH2A-, MY07A-, CNGA3-, and CNGB3-associated retinal disease." (PMID 33039401, 2021). "However, in 2017, the FDA approved a subretinal delivery of AAV2-mediated voretigene neparvovec-rzyl (Luxturna®, Spark Therapeutics, Inc., Philadephia, PA, USA) for the treatment of inherited biallelic RPE65 mutation-associated retinal dystrophy." (PMID 33562561, 2021). "A year later, voretigene neparvovec was approved by the European Medicines Agency for a similar indication: the treatment of adult and pediatric patients with vision loss due to inherited retinal dystrophy caused by confirmed biallelic RPE65 variants and who have sufficient viable retinal cells." (PMID 34281261, 2021). "RPE65-associated inherited retinal dystrophy (RPE65-IRD) is an early-onset retinal degeneration." (PMID 34830511, 2021). "In 2017, voretigene neparvovec (Luxturna®, Spark Therapeutics, Philadelphia, PA, USA) gene therapy was approved by the US Food and Drug Administration for the treatment of patients with confirmed biallelic RPE65 mutation-associated retinal dystrophy and viable retinal cells." (PMID 34281261, 2021). "Mutations in RPE65 have been associated with a number of inherited retinal dystrophies (IRD)." (PMID 32455741, 2020). "Although one gene therapy for RPE65-linked retinal dystrophies is available, clinical interventions to treat other widespread retinal dystrophies based on optogenetics and stem cells are still in preclinical experimentation and/or in early phases of testing in humans." (PMID 33195139, 2020). "Voretigene neparvovec appears to be a relatively safe therapy that could dramatically improve the vision of those with biallelic RPE65 mutation-associated retinal dystrophy." (PMID 30805203, 2019). "Patients with biallelic RPE65 mutation-associated retinal dystrophy." (PMID 33681517, 2019). "Mutations in the RPE65 gene are associated with Leber’s congenital amaurosis type 2 or early onset severe retinal dystrophy, depending on the age of onset of severe visual impairment, which may vary widely in affected individuals." (PMID 28280483, 2017). "Early-onset severe retinal dystrophy (EOSRD) is one of phenotype of all RPE65 mutations." (PMID 25383945, 2014). "To date, multiple missense mutations in the RPE65 gene have been identified in patients with inherited retinal dystrophies, and a wide range of disease severity has been associated with RPE65 mutations, from congenital blindness LCA to adult-onset retinitis pigmentosa." (PMID 22509104, 2012). "MERTK-related retinal dystrophies share many features with those due to RPE65 mutations and could therefore be a good target for future viral-mediated gene therapy in humans." (PMID 21677792, 2011).
Retinal dystrophy (continued). "This rod dysfunction in the superior visual field, retinotopically mapping to the inferior mid-periphery, may represent an early and possibly characteristic feature of mild RPE65-associated retinal dystrophies, which can be missed if only ffERG and FST are tested." (PMID 41251530, 2025). "Indeed, the efficiency of first‐generation rAAV vectors in supplementing the RPE65 gene function resulted in market authorization of voretigene neparvovec for the treatment of RPE65‐linked retinal dystrophies, first in the United States and the following year in Europe." (PMID 33616280, 2021). "Successful treatment has been reported already in children with mild phenotypes of RPE65 retinal dystrophy." (PMID 41251530, 2025). "The approval of voretigene neparvovec-rzyl for RPE65-mediated retinal dystrophy marked a pivotal milestone, establishing proof of concept for durable and safe gene replacement therapy." (PMID 41440982, 2025). "For example, Luxturna, the groundbreaking in vivo gene therapy for hereditary retinal dystrophy, transfers the RPE65 gene to retinal cells using an AAV vector, and its successful approval confirmed the feasibility of gene therapy." (PMID 40657392, 2025). "The Food and Drug Administration (FDA) approval of Luxturna (voretigene neparvovec-rzyl) for treatment of RPE65-related inherited retinal dystrophy (RPE65-IRD) in 2017 was the first regulatory approval of an in vivo gene therapy in the United States." (PMID 40911667, 2025). "This medicament was used as therapy for RPE65-mediated retinal dystrophy – being untreated, it would progress into the completed blindness." (PMID 38819533, 2024). "Recent advancements have accelerated the development and application of gene therapy, exemplified by the approval of Luxturna (voretigene neparvovec) in 2017 for RPE65-mediated retinal dystrophy." (PMID 39439625, 2024). "This strategy’s efficacy has been validated, notably with the FDA’s approval of Luxturna for RPE65-related retinal dystrophy, and is supported by multiple clinical trials." (PMID 39598155, 2024). "The phenotype of the RPE65 retinal dystrophy is mostly an early onset retinal dystrophy with a rapid progression of degeneration leading to blindness in young or middle adult age." (PMID 38376864, 2024). "Several gene therapies for different target genes are being tested in clinical trials currently and one has already been commercialized under the name Luxturna for patients with RPE65-related retinal dystrophy." (PMID 39766861, 2024). "Previous reports have indicated that pathogenic variants in genes such as CEP290, GUCY2D, CRB1, RDH12, and RPE65 are predominantly associated with LCA and early-onset severe retinal dystrophy (EOSRD)." (PMID 39359914, 2024). "Voretigene neparvovec (VN) is the first available gene therapy for patients with biallelic RPE65-mediated inherited retinal dystrophy who have sufficient viable retinal cells." (PMID 38254722, 2024). "Following a series of Phase 1 clinical trials, the first randomized, controlled Phase 3 clinical trial of gene augmentation therapy for RPE65-mediated inherited retinal dystrophy using AAV2-hRPE65v2 (voretigene neparvovec; LUXTURNA) was conducted." (PMID 39408817, 2024). "The study indicates that voretigene neparvovec (LUXTURNA)-mediated RPE65 gene transfer improves functional vision in RPE65-mediated inherited retinal dystrophy." (PMID 39408817, 2024). "Recently, the food and drug administration (FDA) approved Luxturna, an AAV-based gene therapy for treating RPE65-positive retinal dystrophy, which marked a clinical milestone." (PMID 37891793, 2023). "Along with RPE65-mediated IRDs, other monogenic retinal dystrophies have been the focus of gene therapy studies, particularly for ABCA4 and RS1-related IMDs." (PMID 37298674, 2023).
Retinal dystrophy (continued). "Current examples of this strategy include Zolgensma® for spinal muscular atrophy and Luxturna® for RPE65-related retinal dystrophy, both of which are approved for listing, illustrating the safety and feasibility of this strategy for future applications." (PMID 37008065, 2023). "Two articles examined the safety and efficacy of AAV-mediated retinal pigment epithelium-specific protein 65 kDa (RPE65) gene replacement therapy in patients with inherited retinal dystrophies." (PMID 37240368, 2023). "RPE65-associated LCA comprises around 4% to 16% of reported cases, representing one of the most severe forms of inherited retinal dystrophy." (PMID 38264046, 2023). "LUXTURNA targets the RPE65 gene to treat inherited retinal dystrophy, while Zolgensma targets the SMN1 gene in motor neurons to treat spinal muscular atrophy." (PMID 37895887, 2023). "All of the genes included in the new recommendations were already on our list with the exception of RPE65, a retinal dystrophy gene with a new gene therapy." (PMID 36579594, 2022). "Luxturna and Zolgensma are adeno-associated virus (AAV) gene therapies for RPE65 mutation-associated retinal dystrophy and spinal muscular atrophy (SMA), replacing the dysfunctional alleles of the RPE65 or SMN1 gene, respectively, with their functional copies." (PMID 36266673, 2022). "The novel gene therapy voretigene neparvovec is the first approved causative treatment option for this devastating eye disease and is specifically designed to treat RPE65-mediated retinal dystrophies." (PMID 36672611, 2022). "In patients with inherited retinal dystrophy (IRD), precise genetic diagnosis is an indispensable approach as it is required to establish eligibility for the genetic treatment of RPE65-associated IRDs." (PMID 36547097, 2022). "This therapy, approved for treatment of biallelic RPE65 inherited retinal dystrophy, uses an adeno-associated virus (AAV) 2-based vector that encodes the RPE65 transgene." (PMID 36362657, 2022). "Regarding viral toxicity, the vector used for RPE65 retinal dystrophy (Luxturna, Spark Therapeutics Inc., USA) included a strong ubiquitous promoter that targets multiple cell types, including the RPE and the photoreceptors." (PMID 33445564, 2021). "Luxturna rAAV is based on the AAV2 serotype (rAAV2) and delivers a functional copy of the RPE65 (retinal pigment epithelium-specific 65 kDa protein) gene to the retinal pigment epithelial cells of patients with retinal dystrophy." (PMID 34372542, 2021). "It is indicated for patients for RPE65-mediated inherited retinal dystrophy and improves vision by restoring RPE65 protein levels." (PMID 33816449, 2021). "–3 In 2008, gene therapy with unilateral injection of the recombinant adenoviral vector voretigene neparvovec (VN) in three patients with RPE65-related inherited retinal dystrophy (RPE65-IRD) was performed, and improvements in visual function were noted." (PMID 34554209, 2021). "A recent analysis of Luxturna (voretigene neparvovec-rzyl) for the treatment of a rare retinal dystrophy (RPE65-mediated blindness), for example, looked at FDA review documents written prior to the drug’s December 2017 approval." (PMID 33043412, 2020). "Luxturna (US FDA.2017/EMA.2018), the only gene product related to ocular diseases was assessed in a phase III clinical trial of 31 patients with RPE65-mediated inherited retinal dystrophy." (PMID 33392179, 2020). "Human RPE65 mutations cause a spectrum of retinal dystrophies that result in blindness (RP20, LCA2)." (PMID 31379919, 2019). "Genetic etiologies of retinal dystrophy causing both autosomal dominant and recessive disease have been described in the literature and include RHO, RP1, BEST1, GUCY2D, RAX2, and RPE65." (PMID 31856884, 2019). "Several of them are also implicated in other retinal dystrophies: CRB1, RPE65, RDH12and SPATA7are associated with both LCA and early-onset retinal dystrophy (EORD), which often overlap." (PMID 20683928, 2010).